CD4 (CD4 molecule)
Diseases named in the same sentence as CD4 in open-access papers (continued):
Sharing a sentence is not in itself a finding about the gene and the disease.
Immunodeficiency (continued). "In parallel, partial CD4 T cell immunodeficiency is compensated for by increased CD4 T cell proliferation, and impairs GALT barrier function, leading to increased bacterial translocation, which in turn activates innate sensing." (PMID 41373539, 2025). "Advanced immunodeficiency (CD4 level: 200–500 C/mm3) was identified as a predictive factor for anemia in PLWH in this study (OR = 2.88 [0.82–10.11]; p=0.097)." (PMID 40809818, 2025). "They analyzed CD4 subsets and IL-17 responses and found that SLT is associated with clinical features of immunodeficiency due to reduced IL-17 responses and that sodium depletion leads to changes in the ionic environment." (PMID 40303555, 2025). "Regarding the immune status of patients, the CD4 count was mostly < 200 C/mm3 in the population (65.67%), reflecting severe immunodeficiency." (PMID 40809818, 2025). "This created an immunodeficiency state severe enough to be compared to advanced HIV (CD4+ <0.2×109/L), crippling antiviral surveillance and permitting uncontrolled CMV replication." (PMID 41479888, 2025). "ADCs were associated with detectable viral load (>50 copies/mL) and lower CD4+ counts, reinforcing their link with advanced immunodeficiency." (PMID 41003137, 2025). "Our findings indicate that PWID with mild to moderate immunosuppression (CD4 count of 200 cells/mm3 – 500 cells/mm3) had better chances of being retained compared to those with severe immunodeficiency (CD4 count < 200 cells/mm3)." (PMID 41200374, 2025). "Immune dysfunction, marked by CD4+ T cell immunodeficiency with normal immunoglobulin levels, was observed." (PMID 39949750, 2025). "Flow cytometry further confirmed that INRs exhibited diminished CD4+ T cell counts, increased PD‐1+ and HLA‐DR+ expression, and reduced resting memory B cells, reflecting persistent immune dysfunction." (PMID 41084320, 2025). "The degree of immune dysfunction, particularly reflected by CD4+ T-cell counts, plays a pivotal role in the clinical presentation, treatment response, and prognosis of HIV-associated lymphomas." (PMID 40606992, 2025). "It has been shown to induce immune dysfunction in vascular endothelial cells and immune cells including CD4+ T cells and monocytes." (PMID 39996729, 2025). "Immune dysfunction persists in PLWH with a low CD4/CD8 ratio, despite successful ART and normal CD4 recovery." (PMID 40990014, 2025). "The type of lymphoma was significantly influenced by the degree of CD4 cell depletion and immune dysfunction.Patients with CD4+ T-cell depletion are more likely to develop aggressive subtypes such as DLBCL, PEL, or PBL." (PMID 40606992, 2025). "There were more changes within T-cell subsets in those with a CD4/CD8 ratio below 0.76, while a cut-off value below 0.4 showed the strongest association with immune dysfunction, which also concerned NK+ cells." (PMID 40303366, 2025). "The CD4/CD8 ratio has emerged as a useful indicator of immune dysfunction and comorbid conditions in people living with HIV (PLWH)." (PMID 40303366, 2025). "The CD4/CD8 ratio has emerged as a useful marker of immune dysfunction in people living with HIV (PLWH)." (PMID 40303366, 2025). "Among them, 20% of the patients (10/50 cases) had immune dysfunction with CD4+ T lymphocyte counts below 200 cells/μL." (PMID 40109771, 2025). "PLWH who fail to restore a normal CD4+/CD8+ ratio despite adequate CD4+ count gains often exhibit persistent immune dysfunction and inflammation." (PMID 40868140, 2025). "Other immunological markers—such as elevated CD8+ T cell counts and a reduced CD4/CD8 ratio—also reflect immune dysfunction specific to HIV." (PMID 41226717, 2025). "People living with chronic HIV (PLWH) show immune dysfunction, despite viral suppression and normal CD4 recovery, particularly those with low CD4/CD8 ratios." (PMID 40990014, 2025). "SAMe also enhances CD4+ T-cell survival, positively affecting systemic survival, especially in individuals with immune dysfunction due to alcohol abuse." (PMID 41199753, 2025).
Immunodeficiency (continued). "This suggests that once CD4+ T-cell counts are restored under ART, the impact of prior immunodeficiency on NHL risk diminishes, and greater emphasis should be placed on current immune status." (PMID 40723865, 2025). "Combined antiretroviral therapy (cART) has been proven to successfully suppress viral replication, increase CD4+ T cell counts, and reverse clinically significant immunodeficiency, thus reducing morbidity and mortality." (PMID 38400997, 2024). "Again, to draw a parallel between immune response and magnitude of inflammation in HIV infection, we correlated cellular activation of CD4+ T cells and degree of immunodeficiency based on CD4+ T cell count in untreated PLHIV." (PMID 38902613, 2024). "Changes in the levels of T lymphocytes (CD3+, CD4+, and CD8+), B lymphocytes (CD3−CD19+), immunoglobulins (IgG, IgM, and IgA), and cytokines (IL-1β, IL-2R, and IL-6) often indicate immune deficiencies in the body." (PMID 39055621, 2024). "Transgenic K14E6/E7 mice with established high-grade anal dysplasia were treated topically at the anus with the protease inhibitor saquinavir (SQV) in the setting of CD4+ T-cell depletion to mimic immunodeficiency." (PMID 39339897, 2024). "Like our findings, a considerable proportion of patients in both groups had CD4 < 200, indicating an advanced immunodeficiency state." (PMID 38251391, 2024). "HIV infects CD4+ T cells and forms a chronic infection, resulting in a depletion of CD4+ T cells and severe immunodeficiency." (PMID 39248154, 2024). "Given these clinical limitations, we utilized CD4 T cell depletion studies in our mouse model to best recapitulate immunodeficiency abnormalities in the setting of treatment." (PMID 39339897, 2024). "Suppressing HIV replication rapidly increases peripheral blood CD4+ T cell counts and reverses the immunodeficiency, although this is often incomplete." (PMID 39057767, 2024). "We suggest that the CD4/CD8 cell ratio (or IHGs) can be utilized to gain insight into anticipated complications related to a patient’s immunodeficiency by using more well-understood monogenetic diseases with similar CD4/CD8 cell ratios as a guide." (PMID 39728019, 2024). "Many immunodeficiencies lack enough data to fully assess their relationship with the CD4/CD8 ratio due to small patient populations." (PMID 39728019, 2024). "Given these promising results, we sought to evaluate topical SQV’s efficacy in a mouse model in which CD4 cells were depleted to represent immunodeficiency." (PMID 39339897, 2024). "The presented mouse model does, in part, recapitulate immunodeficiency states, as several of the animals who were CD4-depleted developed lymphoma, a known malignancy in the setting of immunosuppression." (PMID 39339897, 2024). "By integrating the MR results, it can be inferred that the gene expression of NEK7 and LHX9 in Activated & resting Treg & CD4 + cell plays a crucial role in carcinogenesis and immune dysfunction." (PMID 38902711, 2024). "The CD4+/CD8+ ratio serves as a sensitive indicator for clinical diagnosis of human immune dysfunction.CD3-CD16+CD56+ cells refer to natural killer (NK) cells, which are vital components of the immune system." (PMID 39703509, 2024). "This study aims to provide a comprehensive overview of how MSCs and their secreted extracellular vesicles (EVs) modulate CD4+T cells in immune diseases." (PMID 39758422, 2024). "The human immunodeficiency virus (HIV) primarily targets clusters of differentiation 4 (CD4)+ T cells and other immune cells, leading to immune dysfunction." (PMID 39238692, 2024). "This profile highlighted that the immunopathogenic factors in EN predominantly relate to the immune disorder of B cells and their subsets, as well as the functional abnormalities within immune cell subsets of CD4+ T cells, CD8+ T cells, and γδ T cells." (PMID 39669572, 2024).
Immunodeficiency (continued). "Meanwhile, NRP1 was recently shown to have an immune suppressive role in CD4+ T cells and regulatory T cells in immune diseases and tumor immunity." (PMID 38994453, 2024). "Overall, this research aims to enhance our understanding of the mechanisms behind MSC-mediated regulation of CD4+T cells and provide insights into the potential use of MSCs and EVs as therapeutic tools in immune diseases." (PMID 39758422, 2024). "Clearly, the presence of CD4+TEM associates with an immune balance seen in LTBI in our model and a decreasein the frequency of this cell type contributes to immune dysfunction that cART + 3HP failsto mitigate." (PMID 39257997, 2024). "For patients with combined immunodeficiency, the mean was 51 × 106 cells for CD4 response and 117 × 106 cells for CD8 response." (PMID 38132279, 2023). "In patients with common variable immunodeficiency, there was a very poor number, if any, of S-specific CD4+ and CD8+ T cells expressing cytokines (IFN-γ, IL-2, and TNF-α)." (PMID 38132279, 2023). "There is currently no cure for HIV infection although adherence to effective antiretroviral therapy (ART) suppresses replication of the virus in blood, increases CD4+ T-cell counts, reverses immunodeficiency, and increases life expectancy." (PMID 38140626, 2023). "In total, 72 PLWH that were asymptomatic or with mild immunodeficiency (CD4 counts ≥200/mm3) and suppressed virology, and 362 healthcare workers of our hospital were enrolled." (PMID 37731482, 2023). "Remarkably, vaccination with live, short-lived ZNF2oe cells in CD4-depleted hosts still provides strong protection to these hosts with preexisting immunodeficiency at the time of vaccination." (PMID 37338404, 2023). "In patients with combined immunodeficiency, the CD4 lymphocyte response was characterized by both IFN-γ and IL-2 production." (PMID 38132279, 2023). "In Taiwan, this additional dose is endorsed even for those who are asymptomatic or have mild immunodeficiency with CD4 counts ≥ 200/mm3 and suppressed virus load." (PMID 37731482, 2023). "Immune deficiencies vary in severity but typically involve reduced levels of CD3+, CD4+, and CD8+ T lymphocytes, resulting in mildly impaired cellular immunity 28-30." (PMID 37790845, 2023). "But, immunodeficiency, especially CD4 lymphocyte cell count, is the most significant predicted risk factor for cancer in HIV patients." (PMID 36708066, 2023). "Strikingly, the use of C188-9, a small molecule targeting STAT3, mitigates colitis in a murine immunodeficiency model receiving eEF2K knockout (KO) CD4+ T cells." (PMID 37875468, 2023). "Most clinicians rely on three main criteria: a net immunodeficiency estimate (eg CD4 T-cell count), MTB specific T cell responses (“LTBI test”), and active TB exclusion." (PMID 37257071, 2023). "CD4+ T cell count and viral loads are also measured to check the degree of immunodeficiency and the rate of immune destruction respectively that will indicate the disease progression/ staging." (PMID 37214076, 2023). "This phenomenon is probably related to the immunodeficiency state of pregnant women, probably related to hormonal influence or the decreased cell-mediated immunity with a decreased CD4/CD8 ratio." (PMID 37956163, 2023). "Highly activated immune disorders of T-receptor cells and CD4+ lymphocytes have also been observed in LGTB, leading to implantation failure." (PMID 38075032, 2023). "Celiac disease (CeD) is a T-cell-mediated immune disease, in which gluten-derived peptides activate lamina propria effector CD4+ T cells." (PMID 37833882, 2023). "We found that immune dysfunction, as measured by peripheral CD4+ T cells, CD8+ T cells, CD19+ B cells, and NK cells, was associated with a higher risk of LVH." (PMID 37273870, 2023). "The decrease of CD4+/CD8+ ratio indicates that defective T cell immune function and immune system disorder can cause tumor occurrence." (PMID 38223622, 2023).
Immunodeficiency (continued). "Purpurin played an anti-inflammatory role by inhibiting IL-6, TNF-α, and IL-1β and increasing IL-10, and regulated immune disorder by decreasing the CD4+/CD8+ ratio and increasing the FOXP3 level." (PMID 36615560, 2023). "By contrast, CD4+ T cells from Ess2-knockout mice show aberrant expression related to metabolism and immune diseases (GEO dataset: PRJNA575280)." (PMID 37524814, 2023). "The differentiation of naïve CD4+ T cells into various lineages of Th cells is crucial in many immune diseases, and Th2 cell differentiation from naïve CD4 + T cells contributes to the onset of Th2 CRSwNP." (PMID 38037054, 2023). "An integrative computational modelling approach was developed to identify effective therapeutic agents for CD4+ T cell-mediated immune disorders." (PMID 38138860, 2023). "INRs are unable to maintain the basic normal immune function of the body due to low CD4+ T cell counts and exhibit severe immune dysfunction." (PMID 37608956, 2023). "RFXANK mutations are prevalent in bare lymphocyte syndrome (BLS) group B, an immunodeficiency disorder affecting CD4+ T and B cells." (PMID 37040172, 2023). "The origin of the impaired CD4 T-cell response and immunodeficiency of HIV-infected patients is still only partially understood." (PMID 35392090, 2022). "More than 50% of PLWH during both periods presented with severe immunodeficiency (CD4 <200) at baseline; this was low compared to other SSA cohorts and other HICs." (PMID 36048901, 2022). "IL-7 acts extensively on cells of the adaptive immune system, promoting the proliferation and survival of primary and memory CD4+/CD8+ T cells, and can reverse the immune deficiency of sepsis." (PMID 36389695, 2022). "There was a predominance of males aged 50-59 years, with severe immunodeficiency upon admission (29.7%), and with a CD4+ T lymphocyte count below 200 cells in 62 (46.3%) of patients." (PMID 35352767, 2022). "Approximately 25% (13/52) of subjects suffered from severe immunodeficiency with CD4+ count 15% or <200 cells/μL, all of them aged > 5 years." (PMID 36355894, 2022). "Children with mild immunodeficiency (CD4 count or percent above the threshold) had a longer OIs-free survival time than children who presented with severe immunodeficiency (CD4 count or percent below the threshold)." (PMID 36536709, 2022). "More than a third of the children, 308 (42.72%), had CD4 counts below the threshold for severe immunodeficiency." (PMID 35222650, 2022). "Nearly three-fourths (73.6%) of the children had CD4 count or percent above the threshold for severe immunodeficiency." (PMID 35978382, 2022). "Immune function test indicated immunodeficiency (CD4+ T lymphocyte 192/mL, CD8+ T lymphocyte 168/mL, CD3+ T lymphocyte 380/mL, serum C3 0.81 g/L, serum C4 0.08 g/L)." (PMID 36246283, 2022). "Most of the studies we refer to emphasise the positive correlation between the occurrence of CNS neurological diseases in HIV-positive patients with a stage of immunodeficiency characterised by a low CD4 T-lymphocyte count and an uncertain prognosis." (PMID 36011138, 2022). "The rate of severe and moderate immunodeficiency in this study was 29.7% and 23.6%, respectively, with 46.3% of patients on admission with CD4+ counts under 200 cells and high viral load." (PMID 35352767, 2022). "A concern of using CD4 as a target antigen, however, is depletion of CD4 helper T-cells and subsequent immunodeficiency." (PMID 35955734, 2022). "For HIV-negative hosts with double or multiple opportunistic, disseminated infections and high serum IgG and globulin levels, low CD4+T cell count, and an increase in inflammatory marker levels, positive AIGA-associated immunodeficiency should be considered." (PMID 35641599, 2022). "IRIS was uncommon in the present study (1.4%) although participants had advanced immunodeficiency and had robust increases in CD4+ T-cell counts." (PMID 36008855, 2022).
Immunodeficiency (continued). "Outpatients and inpatients are eligible for mandatory HIV testing due to clinical symptoms of immunodeficiency tend to have lower baseline CD4 counts." (PMID 36339239, 2022). "An evident increase of CD8+ cells with a concomitant decrease of CD4+ cells can signify immunodeficiency and subclinical infection." (PMID 35743844, 2022). "The lowest CD4 + T cell count measured prior to receiving live vaccination for patients with combined and syndromic immunodeficiencies were 0.910 and 0.610 × 109/L, respectively, while the lowest CD8 + T cell counts was 0.341 and 0.210 × 109/L respectively." (PMID 35397595, 2022). "The CMV fatal outcome corresponds with severe immunodeficiency (usually CD4 < 100 cells/μL) and virome, so CMV in particular seems to be an evolutionary mechanism for eliminating immunocompromised individuals." (PMID 36076989, 2022). "In contrast, we did not observe a correlation between the frequencies of HLA-DR+ CD38+ Tc17 cells (that have more persistent dysfunction), and the CD4:CD8 ratio (rho = − 0.01, P = 0.9), associated with immune dysfunction in HIV infection." (PMID 36104716, 2022). "A previous study reported that in CHB, impaired helper CD4+ T cells was considered to be a central component of overall HBV-specific immune dysfunction." (PMID 35865540, 2022). "Studying the impact of telomere shortening on CD4+ T cells and especially Th1 effector function can provide a better understanding on immune dysfunctions in elderly." (PMID 35321714, 2022). "Increasing evidences reveal that the downregulation of TIPE2 in CD4+ T cells enable the animals resistant to immune disorders by reducing the expression levels of apoptotic genes and immunosuppressive factors." (PMID 35572554, 2022). "Specifically, the selective loss of naive CD4+ T cells, naive CD8+ T cells, and memory CD4+ T cells, and the expansion of memory and effector CD8+ T cells skew the CD4/CD8 ratio, reflecting host immune disorders caused by chronic HIV-1 infection." (PMID 35351857, 2022). "Abnormal lncRNA expression can influence the emergence, development, and prognosis of various immune diseases by controlling CD4+ T-cell differentiation." (PMID 35794862, 2022). "MS is classically considered to be an immune disease initiated by the dysregulation of CD4+ Th1 and Th17 cells, thus its role in the pathogenesis of the disease is quite well established." (PMID 35563559, 2022). "Patients with HIV, or otherwise immunocompromised conditions, showed obvious immune dysfunction based on the impairment of CD4, CD8, and complement levels of C3 and C4." (PMID 35492344, 2022). "CD is a T-cell mediated immune disease in which gliadin-derived peptides activate lamina propria effector CD4 + T cells." (PMID 36513696, 2022). "The factors of age, sex, diabetes, immune system diseases, neutrophil counts, lymphocyte counts, and CD4/CD8 ratio were significantly correlated with false-positive and true-negative (known as specificity) QFT-GIT results." (PMID 36288019, 2022). "Previous studies suggested that immune system disorders in females with TS included lower levels of IgG, a lower percentage of CD4+ T cells and a smaller CD4+ T cell to CD8+ T cell ratio than were observed among healthy controls." (PMID 35273637, 2022). "The association of CD4/CD8 ratio, which is used as surrogate marker for immunosenescence and immune dysfunction, with high PAA is also observed in our study." (PMID 36585655, 2022). "Increased inflammatory activity of CD4+ T lymphocytes plays a key role in the immune dysfunction of patients with NAFLD." (PMID 35069014, 2022). "The CD4/CD8 ratio is widely used as a clinical marker of disease progression during HIV infection since it is associated with clinical outcome, immune dysfunction, and viral reservoir size in the ARV-treated individuals." (PMID 35311550, 2022).